EIF3L (eukaryotic translation initiation factor 3 subunit L)
Description:
Component of the eukaryotic translation initiation factor 3 (eIF-3) complex, which is required for several steps in the initiation of protein synthesis. The eIF-3 complex associates with the 40S ribosome and facilitates the recruitment of eIF-1, eIF-1A, eIF-2:GTP:methionyl-tRNAi and eIF-5 to form the 43S pre-initiation complex (43S PIC). The eIF-3 complex stimulates mRNA recruitment to the 43S PIC and scanning of the mRNA for AUG recognition. The eIF-3 complex is also required for disassembly and recycling of post-termination ribosomal complexes and subsequently prevents premature joining of the 40S and 60S ribosomal subunits prior to initiation. The eIF-3 complex specifically targets and initiates translation of a subset of mRNAs involved in cell proliferation, including cell cycling, differentiation and apoptosis, and uses different modes of RNA stem-loop binding to exert either translational activation or repression. (Microbial infection) In case of FCV infection, plays a role in the ribosomal termination-reinitiation event leading to the translation of VP2.
Synonyms: EIF3EIP; EIF3S6IP; HSPC021; HSPC025; MSTP005; EIF3S11
Tractability: Small molecule: a structure with a bound ligand is known. PROTAC: ubiquitination databases record sites on it; its protein half-life has been measured.
Gene: Protein-coding gene on chromosome 22 (37,848,868 to 37,889,407, forward strand). Ensembl gene ENSG00000100129.
Subcellular location: Cytoplasm
Subcellular location (Human Protein Atlas): Nucleoli; Nucleoplasm
Pathways (Reactome):
Metabolism of proteins: Formation of a pool of free 40S subunits; Formation of the ternary complex, and subsequently, the 43S complex; GTP hydrolysis and joining of the 60S ribosomal subunit; L13a-mediated translational silencing of Ceruloplasmin expression; Ribosomal scanning and start codon recognition; Translation initiation complex formation
Gene Ontology:
Molecular function: protein binding; RNA binding; translation initiation factor activity
Biological process: translational initiation; viral translational termination-reinitiation; formation of cytoplasmic translation initiation complex; cytoplasmic translational initiation
Cellular component: eukaryotic translation initiation factor 3 complex; membrane; cytosol; cytoplasm; eukaryotic 43S preinitiation complex; eukaryotic 48S preinitiation complex; fibrillar center; nucleolus; nucleoplasm; protein-containing complex; synapse
Genetic constraint (gnomAD): Loss-of-function variants: 32 observed, 73.46 expected, observed/expected ratio (o/e) 0.44, 90% interval 0.33 to 0.58. The upper end of that interval is the gene's LOEUF score, 0.58, which puts it in group 2 of 6, group 1 being the genes least tolerant of losing a copy. Missense variants: 454 observed, 700.66 expected, observed/expected ratio (o/e) 0.65, 90% interval 0.6 to 0.7. Synonymous variants: 248 observed, 257.12 expected, observed/expected ratio (o/e) 0.96, 90% interval 0.87 to 1.07.
Homologues: Orthologues: chimpanzee EIF3L (100% identical), dog EIF3L (99% identical), mouse Eif3l (99% identical), rabbit EIF3L (99% identical), guinea pig EIF3L (98% identical), rat Eif3l (98% identical), macaque EIF3L (95% identical), pig EIF3L (93% identical), tropical clawed frog eif3l (92% identical), zebrafish eif3s6ip (91% identical), dog EIF3L (80% identical), dog EIF3L (79% identical), and 3 more.
Diseases named in the same sentence as EIF3L in open-access papers:
EIF3L is named in the same sentence as 12 diseases in open-access papers, as found by Europe PMC text mining. Sharing a sentence is not in itself a finding about the gene and the disease. The quoted sentences say what the papers report.
virus infection (3 papers, 2013 to 2022). "The aim of this study was to characterize the interaction of the NS5 protein with eukaryotic translation initiation factor 3 subunit L (eIF3L) and to evaluate the role of eIF3L in yellow fever replication." (PMID 23800076, 2013). "During viral infection, more attention may be paid to the role of eIF3L in viral translation." (PMID 36366532, 2022). "The eIF3L can interact with the M protein of PEDV and significantly inhibit virus replication, but how eIF3L inhibits virus infection remains to be further explored." (PMID 36366532, 2022).
glioma (2 papers, 2019 to 2023). A benign or malignant brain and spinal cord tumor that arises from glial cells (astrocytes, oligodendrocytes, ependymal cells). "By contrast, the expression of eIF3a and eIF3l was decreased in higher grade gliomas and was associated with better overall survival (Both HR < 1 and P < 0.05)." (PMID 31171919, 2019). "In both the CGGA and TCGA datasets, the expression levels of eIF3d, eIF3e, eIF3f, eIF3h and eIF3l highly were associated with the IDH mutant status of gliomas." (PMID 31171919, 2019). "The results indicated that the expression levels of eIF3a, eIF3b, eIF3i, eIF3k, eIF3l and eIF3m were significantly (P < 0.05) correlated to the OS of glioma patients in both datasets." (PMID 31171919, 2019).
prostate carcinoma (1 paper, 2025). A carcinoma that arises from epithelial cells of the prostate gland. "Androgens significantly increase the palmitoylation level of eIF3L (a subunit of eIF3), promoting prostate cancer cell proliferation by enhancing translation rates." (PMID 40977744, 2025). "Androgen-induced elevation of eIF3L levels may serve as an early biomarker for prostate cancer." (PMID 40977744, 2025).
tumor (4 papers, 2016 to 2023). "Levels of nine eIF3 subunits involving eIF3A, eIF3B, eIF3C, eIF3D, eIF3E, eIF3H, eIF3I, eIF3J, and eIF3M were significantly increased in cancer tissues, whereas the eIF3L expression level in tumours was independently decreased than that of normal tissues (p < 0.05)." (PMID 31885740, 2019).
cancer (2 papers, 2019 to 2023). A tumor composed of atypical neoplastic, often pleomorphic cells that invade other tissues. "Another subgroup of PPIs presumably perturbed by cancers is characterized by negative or near-zero r-values in cancers and positive r-values of gene co-expression in conditionally normal tissues, for example, C1orf131/EIF3L, C19orf53/APEX1, C1orf198/PPP2R1A and C1orf198/ARHGEF1." (PMID 37373333, 2023).
infection (1 paper, 2013). The state of being infected such as from the introduction of a foreign agent such as serum, vaccine, antigenic substance or organism. "At 48 h after infection, a slight inhibition of yellow fever virus replication (but without statistical significance) was observed in the pCDNAFlag-eIF3L-transfected cells compared to the controls." (PMID 23800076, 2013). "In addition, we also overexpressed eIF3L in Vero cells and infected them with a multiplicity of infection (M.O.I.)of 1 for the YFV 17D virus." (PMID 23800076, 2013).
neurodegenerative disease (1 paper, 2023). A disorder of the central nervous system characterized by gradual and progressive loss of neural tissue and neurologic function. "The miR-124-3p enriched for three hubs (Gmcl1, Snx24, and Eif3l) of those modules negatively correlated with the HNS group and enriched for inflammatory pathways or neurodegenerative diseases." (PMID 37355705, 2023).
EIF3L also shares sentences with these, for which no sentence is quoted: breast carcinoma (1 paper); dementia (1); ductal breast carcinoma (1); ductal breast carcinoma in situ (1); kidney adenocarcinoma (1).